ZNF432 (zinc finger protein 432)
Description:
Homologous recombination repressor that functions as a poly(ADP-ribose) (PAR) reader regulating DNA damage response and PARP inhibition. Once recruited to DNA lesions via DNA-, in a PAR-dependent mechanism, stimulates PARP1 activity. Binds preferentially ssDNA and inhibits EXO1-mediated resection, probably through a PAR-independent DNA-binding mechanism.
Synonyms: KIAA0798
Tractability: No criterion of Open Targets' tractability assessment is met for any kind of drug.
Gene: Protein-coding gene on chromosome 19 (52,031,378 to 52,095,738, reverse strand). Ensembl gene ENSG00000256087.
Subcellular location: Nucleus
Subcellular location (Human Protein Atlas): Nucleoplasm
Pathways (Reactome):
Gene expression (Transcription): Generic Transcription Pathway
Gene Ontology:
Molecular function: damaged DNA binding; protein binding; protein-macromolecule adaptor activity; DNA binding
Biological process: DNA damage response; regulation of DNA-templated transcription
Cellular component: nucleolus; nucleoplasm; nucleus
Genetic constraint (gnomAD): Loss-of-function variants: 11 observed, 15.65 expected, observed/expected ratio (o/e) 0.7, 90% interval 0.44 to 1.16. The upper end of that interval is the gene's LOEUF score, 1.16, which puts it in group 5 of 6, group 1 being the genes least tolerant of losing a copy. Missense variants: 793 observed, 833.98 expected, observed/expected ratio (o/e) 0.95, 90% interval 0.9 to 1.01. Synonymous variants: 247 observed, 266.69 expected, observed/expected ratio (o/e) 0.93, 90% interval 0.83 to 1.03.
Homologues: Orthologues: chimpanzee ZNF432 (99% identical), macaque ZNF432 (96% identical), dog ZNF432 (84% identical), guinea pig ZNF432 (79% identical). Paralogues in human: ZNF615 (63% identical), ZNF268 (47% identical), RBAK (44% identical), ZNF182 (40% identical), ZNF33B (40% identical), ZNF605 (40% identical), ZNF717 (40% identical), ZNF229 (39% identical), ZNF41 (39% identical), ZNF484 (39% identical), ZNF658 (39% identical), ZNF227 (38% identical), and 164 more.
Diseases named in the same sentence as ZNF432 in open-access papers:
ZNF432 is named in the same sentence as 6 diseases in open-access papers, as found by Europe PMC text mining. Sharing a sentence is not in itself a finding about the gene and the disease. The quoted sentences say what the papers report.
asthma (1 paper, 2023). "Besides being described in 2014 as a gene appearing to influence the effect of inhaled steroids on asthma, there is no biological function assigned to ZNF432." (PMID 37823600, 2023).
ovarian carcinoma (1 paper, 2023). A malignant neoplasm originating from the surface ovarian epithelium. "Considering this interesting finding, we performed gene expression analysis in ovarian cancer tissue samples and we have identified an overall lower expression of ZNF432 in ovarian cancer samples when compared to normal ovary samples." (PMID 37823600, 2023). "To assess the impact of ZNF432 overexpression in a cellular model of high-grade serous ovarian cancer, we chose the ovarian cancer cell line COV362 and an Olaparib-resistant version (COV362-R)." (PMID 37823600, 2023). "Together with the in cellulo viability data, the tumour sample analysis suggests that modulation of ZNF432 expression in ovarian cancer cells could sensitize them to PARPi." (PMID 37823600, 2023). "Our data confirm our assumptions, where we show that downregulation of ZNF432 in U2OS and ovarian cancer cells leads to resistance to PARPi, whereas over-expression rescues this phenotype." (PMID 37823600, 2023). "Based on this analysis, our data clearly demonstrate that the expression of ZNF432 in endometroid ovarian cancer patients is significantly lower compared to the healthy (normal) population (high vs high and low vs low)." (PMID 37823600, 2023). "In addition to ZNF432, an ever-increasing number of ZFPs have been shown to impact genome stability which could eventually lead to the establishment of a predictive ZFP gene signature for PARPi response with prognostic value in ovarian cancer." (PMID 37823600, 2023).
cancer (1 paper, 2022). A tumor composed of atypical neoplastic, often pleomorphic cells that invade other tissues. "Several genes from the zinc finger family, including ZNF577, ZNF649, ZNF615, ZNF614, and ZNF432, are under intense investigation due to their altered methylation status in various cancer types." (PMID 36553064, 2022).
ZNF432 also shares sentences with these, for which no sentence is quoted: tumor (2 papers); glioblastoma (1); serous ovarian cancer (1).